REXO1L1P (REXO1 like 1, pseudogene)
Synonyms: GOR; formerly REXO1L1
Gene: Transcribed processed pseudogene on chromosome 8 (85,661,524 to 85,663,497, reverse strand). Ensembl gene ENSG00000205176.
Subcellular location: Cytoplasm; Nucleus
Diseases named in the same sentence as REXO1L1P in open-access papers:
REXO1L1P is named in the same sentence as 6 diseases in open-access papers, as found by Europe PMC text mining. Sharing a sentence is not in itself a finding about the gene and the disease.
REXO1L1P shares sentences with these, for which no sentence is quoted: autoimmune liver disease (1 paper); breast carcinoma (1); hepatitis C infection (1); malabsorption syndrome (1); neuroblastoma (1); tumor (1).